ANXA4 (annexin A4)
Description:
Calcium/phospholipid-binding protein which promotes membrane fusion and is involved in exocytosis.
Synonyms: PAP-II; ANX4; HEL-S-274; P32.5; PIG28; PP4-X; ZAP36
Tractability: Antibody: its Gene Ontology location is reachable by antibodies, with high confidence; UniProt places it where antibodies can reach, with medium confidence. PROTAC: ubiquitination databases record sites on it; its protein half-life has been measured.
Target class: Ion channel; Annexin; Other ion channel
Gene: Protein-coding gene on chromosome 2 (69,643,808 to 69,827,121, forward strand). Ensembl gene ENSG00000196975.
Subcellular location: Zymogen granule membrane
Subcellular location (Human Protein Atlas): Cytosol
Gene Ontology:
Molecular function: calcium ion binding; calcium-dependent phospholipid binding; calcium-dependent protein binding; identical protein binding; NF-kappaB binding; protein binding; transcription regulator inhibitor activity; phosphatidylserine binding; phospholipase inhibitor activity
Biological process: epithelial cell differentiation; negative regulation of canonical NF-kappaB signal transduction; negative regulation of interleukin-8 production; negative regulation of transcription by RNA polymerase II; negative regulation of tumor necrosis factor-mediated signaling pathway; negative regulation of apoptotic process; signal transduction
Cellular component: cell surface; cytoplasm; extracellular exosome; extracellular matrix; nuclear membrane; nucleus; perinuclear region of cytoplasm; plasma membrane; vesicle membrane; zymogen granule membrane
Genetic constraint (gnomAD): Loss-of-function variants: 28 observed, 35.64 expected, observed/expected ratio (o/e) 0.79, 90% interval 0.58 to 1.08. The upper end of that interval is the gene's LOEUF score, 1.08, which puts it in group 4 of 6, group 1 being the genes least tolerant of losing a copy. Missense variants: 279 observed, 335.39 expected, observed/expected ratio (o/e) 0.83, 90% interval 0.75 to 0.92. Synonymous variants: 108 observed, 129.75 expected, observed/expected ratio (o/e) 0.83, 90% interval 0.71 to 0.98.
Homologues: Orthologues: chimpanzee ANXA4 (100% identical), macaque ANXA4 (99% identical), dog ANXA4 (94% identical), rabbit ANXA4 (94% identical), guinea pig ANXA4 (93% identical), mouse Anxa4 (92% identical), pig ANXA4 (88% identical), rat Anxa4 (79% identical), tropical clawed frog anxa4 (74% identical), zebrafish anxa4 (64% identical), Drosophila melanogaster AnxB9 (49% identical), Drosophila melanogaster AnxB11 (46% identical). Paralogues in human: ANXA5 (57% identical), ANXA11 (57% identical), ANXA8L1 (55% identical), ANXA8 (55% identical), ANXA6 (54% identical), ANXA3 (52% identical), ANXA2 (49% identical), ANXA7 (49% identical), ANXA13 (45% identical), ANXA1 (45% identical), ANXA10 (44% identical), ANXA9 (36% identical).
Diseases named in the same sentence as ANXA4 in open-access papers:
ANXA4 is named in the same sentence as 86 diseases in open-access papers, as found by Europe PMC text mining. Sharing a sentence is not in itself a finding about the gene and the disease. The quoted sentences say what the papers report.
breast carcinoma (19 papers, 2012 to 2024). "ANXA4 was overexpressed in breast cancer tissues and its overexpression stimulated MCF-7 cell migration." (PMID 38417630, 2024). "Knockdown of ANXA4 attenuates migration in breast cancer cells by regulating adhesion-related molecules." (PMID 33628783, 2021). "AnxA4 and AnxA5 are expressed in breast cancer tissues and upregulation of AnxA4 promotes chemo-resistance of breast cancer." (PMID 29416802, 2018). "Throughout the years of investigation Annexin A1 (AnxA1), Annexin A2 (AnxA2), Annexin A3 (AnxA3), Annexin A4 (AnxA4), Annexin A5 (AnxA5), Annexin A6 (AnxA6), and Annexin A8 (AnxA8) have all been identified as potential modulators of breast cancer progression." (PMID 29416802, 2018). "Annexin A4 enhances NF-κB subunit p50 transcriptional activity, and Annexin A1 expression positively correlates with NF-κB activity in breast cancer metastasis." (PMID 25222280, 2014). "Zimmerman and colleagues reported that overexpression of ANXA4 in MCF-7 breast cancer cells accelerated migration in vitro, which is consistent with our result on OVISE cells." (PMID 24244679, 2013). "The decreased abundance of ANXA4 in RELA immunoprecipitate after NF-κB inhibition in our study suggests that ANXA4 interplays with NF-κB also in the breast cancer and could promote metastatic behavior of breast tumors via NF-κB pathway." (PMID 38417630, 2024). "For example, ANXA4 is upregulated and translocated to the nucleus in ovarian clear cell carcinoma and colorectal cancer, and the knockdown of ANXA4 weakens the migration and invasion of ovarian cancer and breast cancer cells." (PMID 39399103, 2024). "ANXA4 was overexpressed in various primary clinical epithelial tumors, such as renal cancer, ovary cancer, gastric cancer, colorectal cancer, breast cancer, laryngeal carcinoma, pancreatic cancer." (PMID 27485544, 2016). "A number of studies have shown that ANXA4 takes part in several biological functions in a Ca2+-dependent manner, including apoptosis and growth control, and that it is overexpressed in ovarian and breast cancers." (PMID 27070597, 2016). "To explore the impact of annexins in breast cancer, we compared the expression of ANXA1, ANXA2 and ANXA4 in MDA-MB-231 and MCF7 cells at the protein and mRNA level." (PMID 38092984, 2023). "This suggests that ANXA4 may not be associated with estrogen dependent initiation of breast cancer." (PMID 37064098, 2023). "In breast cancer, studies have proven that ANXA2, ANXA4, ANXA5, ANXA6, and ANXA7 are required for repair in breast cancer cells, indicating that a network of annexins participate in the plasma membrane repair response." (PMID 34484309, 2021). "The most upregulated proteins by SBP1 induction included DKK1 that inhibits WNT pathway, DHCR7 that controls cholesterol and Vitamin D synthesis, ANXA4 that inhibits NFkB pathway and IL-8, and AGPAT5 that inhibits breast cancer cell proliferation." (PMID 25974208, 2015). "In vitro functional analyses showed that forced overexpression of ANXA4 induced carboplatin resistance in OVSAYO SC-cells, paclitaxel resistance in 293T cells, migration on vitronectin in MCF-7 breast cancer cells, and proliferation in AGS gastric cancer cells." (PMID 24244679, 2013). "In addition, integrating pathway and gene information, we identified five (ID4, ANXA4, CXCL9, MYLK, FBXL7) and six (SQLE, E2F1, PTTG1, TSTA3, BUB1B, MAD2L1) known cancer genes significant for ovarian and breast cancer respectively." (PMID 22759382, 2012).
ovarian carcinoma (16 papers, 2011 to 2024). A malignant neoplasm originating from the surface ovarian epithelium. "The expression rate of both annexin A4 and Lewis y antigen was significantly higher in ovarian clear cell carcinoma than in other subtypes of epithelial ovarian cancer, and are associated with the clinical stages, chemotherapy resistance and poor prognostic." (PMID 29296226, 2017). "Increased levels of annexin A4 have been associated with cisplatin resistance in ovarian cancer and paclitaxel resistance in the lung cancer cell line H460." (PMID 21637840, 2011). "Therefore, we believe that ANXA2 and ANXA4 are closely associated with the tumorigenesis and progression of ovarian cancer." (PMID 31474227, 2019). "Blood levels of ANXA4 have been shown to be increased in hepatocellular cancer and up-regulations in tumor tissue has been detected in colorectal- and ovarian cancer suggesting a tumor promoting effect of this protein." (PMID 37064098, 2023). "The overexpression of Lewis(y), a component of the structure of the ANXA4 membrane protein, induces the chemoresistance of ovarian cancer cells, and ultimately promoting the progression of ovarian cancer." (PMID 34540918, 2021). "ANXA4 was found in various other complications such as renal, gastric cancer, ovary cancer, and buccal squamous cell carcinoma." (PMID 34181340, 2021). "Annexin A4 (ANXA4) is one of the annexin family with high expressions found in gastric, liver, lung, colorectal and ovarian cancers." (PMID 32986366, 2020). "The results suggested that ANXA2 and ANXA4 were correlated with ovarian cancer tumorigenesis and progression." (PMID 31474227, 2019). "Our results also showed that ANXA4 was highly expressed in ovarian cancer, and in particular, it displayed the highest expression level in ovarian clear cell carcinoma." (PMID 31474227, 2019). "Recent studies have shown that ANXA2 is highly expressed in ovarian cancer and that ANXA3 and ANXA4 are involved in cisplatin resistance in ovarian cancer." (PMID 31474227, 2019). "Immunohistochemistry confirmed that there were elevated ANXA4 levels in OCCC and low ANXA4 levels in other ovarian cancer subtypes, suggesting that ANXA4 can serve as an OCCC-specific marker gene." (PMID 29296226, 2017). "Annexin A4 and Lewis y antigen expression in various subtypes of ovarian cancer tissues was detected by immunohistochemistry, and the relation between their expression was examined." (PMID 29296226, 2017). "To create cell lines with a stable ANXA4 knockdown, we analysed ANXA4 expression in ovarian cancer cells using western blotting." (PMID 25277200, 2014). "We first reconfirmed the abundant and significant expression of ANXA4 in CCC against other types of ovarian carcinomas in clinical samples, using IHC as in two preceding reports." (PMID 24244679, 2013). "ANXA4 was found to bind NFKB1/p50 protein and to activate NF-κB signaling pathway in ovarian carcinoma." (PMID 38417630, 2024). "Eight immune factors (IFT57, MAL, ANXA4, SCRN1, LTBR, KIFAP3, HSPA5, and LTN1) were positively correlated with poor prognosis of ovarian cancer, whereas six immune factors (PSMB9, FOXJ1, CTSH, MIF, CTSD, and PSMB8) were negatively correlated with poor prognosis of ovarian cancer." (PMID 34109184, 2021). "In addition, the expression levels of ANXA1, ANXA4, ANXA5, ANXA6, ANXA7 and ANXA13 were lower in ovarian cancer than in the normal controls." (PMID 31474227, 2019). "All 52 CCC specimens demonstrated significant staining for ANXA4 (IHC score 5 or 6) without exception, with P<0.05 against all other types of ovarian carcinomas and LMP tumors." (PMID 24244679, 2013).
gastric cancer (10 papers, 2012 to 2023). A primary or metastatic malignant neoplasm involving the stomach. "H. pylori induces ANXA4 expression and intracellular [Ca2+]i elevation, and is an important risk factor for carcinogenesis that results in gastric cancer." (PMID 22970268, 2012). "ANXA4, a member of the annexins family, has been observed to be overexpressed in gastric tumor tissues and is also associated with the gastric cancer-related H. pylori infection." (PMID 22970268, 2012). "ANXA4 encodes a protein that has been discussed as a possible marker for gastric cancer." (PMID 23555315, 2013). "Because the ANXA4 expression in AGS gastric cancer cells induces expression of membrane proteins RHAMM and LAMP2, we examined the expression of these proteins in OVISE and OVTOKO cells." (PMID 24244679, 2013). "The study began from the identification of ANXA4 as an up-regulated protein in Helicobacter pylori-infected gastric cancer." (PMID 24244679, 2013). "A potential biomarker for gastric cancer is the protein annexin A4 (ANXA4), an intracellular Ca2+ sensor." (PMID 22970268, 2012). "To accomplish this, we monitored the growth rate of gastric cancer cells with different expression levels of ANXA4." (PMID 22970268, 2012). "Recent studies have shown that ANXA4 is considered to be a potential gastric biomarker based on its identification in tissues of gastric cancer patients in proteomic studies." (PMID 22970268, 2012). "These events suggest that ANXA4 could mediate the downstream signal pathway, leading to tumorigenesis in gastric cancer patients with a H. pylori infection." (PMID 22970268, 2012). "In order to further evaluate the cellular function of ANXA4 in the progression of gastric cancer, we explored the link between the two and subsequently demonstrated that ANXA4 may regulate cancer-related genes and propagate the path to cell proliferation." (PMID 22970268, 2012). "Furthermore, we found an overexpression of MMP-9, that promotes tumor invasion and is associated with poor prognosis in gastric cancer, ANXA1 and ANXA4, overexpressed in gastric cancer and associated with proliferation, AREG, that promotes malignant progression in several types of cancer." (PMID 34012923, 2021).
colorectal cancer (8 papers, 2008 to 2024). A primary or metastatic malignant neoplasm that affects the colon or rectum. "In colorectal cancer patients, high expression of ANXA4 was associated with a low survival rate and was reported as a potential biomarker for tumor diagnosis." (PMID 22970268, 2012). "ANXA4, a member of the annexin family, is upregulated in colorectal cancer in addition to enhancing tumor proliferation in human cancers, specifically promoting colorectal cancer tumorigenesis." (PMID 37873786, 2023). "This downregulation of ANXA4 after D8 suggests that the reovirus treatment came into effect in downregulating colorectal cancer tumorigenesis at 8 days after administration." (PMID 37873786, 2023). "Using Gene Expression Omnibus datasets (GEO) [GSE20916 (Poland), Skrzypczak Colorectal; GSE 8671 (Switzerland), and Sabates-Bellver Colon], we found that ANXA4 expression was significantly higher in colorectal cancer tissue than in the normal colonic mucosa." (PMID 33761465, 2021). "In this study, we verified the high expression and membrane-cytoplasm translocation of ANXA4 in colorectal carcinoma (CRC)." (PMID 33761465, 2021). "In this study, we verified the high expression and membrane-cytoplasm translocation of ANXA4 in colorectal carcinoma." (PMID 33761465, 2021). "For annexin A4, a few studies reported its increased expression in clear cell renal cancer and colorectal cancer by using a combination of proteomics tools." (PMID 19691830, 2009). "ANXA4 has been highly expressed in colorectal cancer and contributes to its tumorigenesis." (PMID 37873786, 2023). "Thus, at around the 8-day mark, the reovirus was effective at downregulating ANXA4 and contributing to the suppression of tumorigenesis in colorectal cancer." (PMID 37873786, 2023). "Next, we further showed that CAMK2ɤ was indispensable for high ANXA4 expression in colorectal carcinoma and that the location of ANXA4 location in the cell membrane was Ca2+ dependent; CA1 could also promote ANXA4 aggregation in the cell membrane." (PMID 33761465, 2021). "Annexin A4 is known to form complexes with protein kinase C, and there are 10 isoforms of protein kinase C that have roles in cancer progression (metastasis) and some of these isoforms have been shown to be overexpressed in colorectal cancer." (PMID 18071363, 2008). "In colorectal carcinoma, Ca2+ did not affect the interaction between SUMO1 and ANXA4, and SUMOylation did not affect the membrane-cytoplasm translocation of ANXA4." (PMID 33761465, 2021).
lung cancer (8 papers, 2011 to 2025). A malignant neoplasm involving the lung. "FHIT-mimetic peptide (7–13, QHLIKPS) has been reported to interact with ANXA4 restoring chemosensitivity to paclitaxel in lung cancer cells." (PMID 34901149, 2021). "Fhit peptide also retains the property of the native protein in inhibiting Annexin A4 translocation from cytosol to plasma membrane in A549 and Calu-2 lung cancer cells treated with paclitaxel." (PMID 34901149, 2021). "Among the different peptides designed, one peptide was identified for its capability to bind ANXA4 and reduce cell viability in paclitaxel-treated lung cancer cells." (PMID 34901149, 2021). "Here we report that overexpression of Fhit prevents Annexin A4 translocation from cytosol to plasma membrane in A549 lung cancer cells treated with paclitaxel." (PMID 24223161, 2013). "Interestingly, Fhit peptide also recapitulates the property of the native protein in inhibiting Annexin A4 translocation from cytosol to plasma membrane in A549 and Calu-2 lung cancer cells treated with paclitaxel." (PMID 27166255, 2016). "We recently reported that Fhit is in a molecular complex with annexin A4 (ANXA4); following to their binding, Fhit delocalizes ANXA4 from plasma membrane to cytosol in paclitaxel-resistant lung cancer cells, thus restoring their chemosensitivity to the drug." (PMID 27166255, 2016). "However, given that lung cancers secrete multiple additional factors (e.g., HSPA1A, MFGE8, ANXA4), our approach allows us to study and dissect the role of tumor‐derived EVs independent of other secreted factors." (PMID 40788065, 2025). "To investigate the effects of Fhit/Annexin A4 interaction in vivo with or without paclitaxel in a preclinical model of lung cancer, we performed an experiment on 11 groups of mice (n = 5 mice/group)." (PMID 24223161, 2013). "Intriguingly, Fhit restoration in Fhit-negative lung cancer cells blocks ANXA4 translocation from cytosol to the inner side of plasma membrane during paclitaxel administration, an effect that contribute to chemoresistance, thus sensitizing again cancer cells to the drug." (PMID 27166255, 2016).
hepatocellular carcinoma (6 papers, 2012 to 2023). A malignant tumor that arises from hepatocytes. "Ikaros inhibited the proliferation of tumour cells by downregulating the expression of ANXA4 in hepatocellular carcinoma." (PMID 34109184, 2021). "It is worth mentioning that ANXA4 may be a key factor in hepatocellular carcinoma tumorigenesis, as downregulating ANXA4 expression can inhibit hepatocellular carcinoma proliferation and tumorigenesis in vitro and in vivo." (PMID 36936694, 2023). "It was reported that the increased serum level of ANXA4 might be a promising biomarker for the early detection of hepatocellular carcinoma." (PMID 34540918, 2021). "In hepatocellular carcinoma, the overexpression of ANXA2, ANXA3, ANXA4, ANXA5 and ANXA11 promotes proliferation because ANXA2–ANXA5 affect Wnt/β-catenin, MEK-ERK, PI3K/AKT-HIF-α and other pathways." (PMID 36936694, 2023).
gallbladder cancer (5 papers, 2016 to 2024). "In gallbladder carcinoma, knockdown of ANXA4 resulted in decreased transcription activity of RELA and lower expression of NF-κB target genes; moreover, inhibition of NF-κB was associated with suppressed ANXA4 expression." (PMID 38417630, 2024). "AnxA4 is upregulated in various epithelial cancers, and AnxA4 knockdown reduced xenograft growth of gallbladder cancer cells, possibly by downregulating oncogenic NFκB signaling pathways." (PMID 33810523, 2021). "Moreover, the elevated ANXA4 expression correlated well with invasion depth in patients with gallbladder cancer." (PMID 30404616, 2018). "In gallbladder cancer tissues, the ANXA4 gene was highly expressed." (PMID 30404616, 2018).